NUDT16L1 (nudix hydrolase 16 like 1)
Description:
Key regulator of TP53BP1 required to stabilize TP53BP1 and regulate its recruitment to chromatin. In absence of DNA damage, interacts with the tandem Tudor-like domain of TP53BP1, masking the region that binds histone H4 dimethylated at 'Lys-20' (H4K20me2), thereby preventing TP53BP1 recruitment to chromatin and maintaining TP53BP1 localization to the nucleus. Following DNA damage, ATM-induced phosphorylation of TP53BP1 and subsequent recruitment of RIF1 leads to dissociate NUDT16L1/TIRR from TP53BP1, unmasking the tandem Tudor-like domain and allowing recruitment of TP53BP1 to DNA double strand breaks (DSBs). Binds U8 snoRNA.
Synonyms: SDOS; TIRR
Tractability: PROTAC: UniProt records ubiquitination sites on it; ubiquitination databases record sites on it; its protein half-life has been measured.
Gene: Protein-coding gene on chromosome 16 (4,693,562 to 4,695,861, forward strand). Ensembl gene ENSG00000168101.
Subcellular location: Nucleus
Gene Ontology:
Molecular function: 5'-(N(7)-methylguanosine 5'-triphospho)-[mRNA] hydrolase activity; protein binding; protein homodimerization activity; RNA binding; snoRNA binding; phosphodiesterase decapping endonuclease activity
Biological process: negative regulation of double-strand break repair via nonhomologous end joining; mRNA catabolic process; sno(s)RNA catabolic process
Cellular component: nucleus
Genetic constraint (gnomAD): Loss-of-function variants: 19 observed, 13.33 expected, observed/expected ratio (o/e) 1.43, 90% interval 0.98 to 1.89. The synonymous counts are far from expectation, so gnomAD's model fits this gene poorly and the ratio says little. Missense variants: 341 observed, 249.94 expected, observed/expected ratio (o/e) 1.36, 90% interval 1.25 to 1.49. Synonymous variants: 255 observed, 133.28 expected, observed/expected ratio (o/e) 1.91, 90% interval 1.71 to 1.99.
Homologues: Orthologues: pig NUDT16L1 (98% identical), rat Nudt16l1 (96% identical), mouse Nudt16l1 (96% identical), guinea pig NUDT16L1 (94% identical), dog NUDT16L1 (79% identical), chimpanzee NUDT16L1 (72% identical), tropical clawed frog nudt16 (44% identical), zebrafish zgc:103759 (37% identical). Paralogues in human: NUDT16 (51% identical).
Diseases named in the same sentence as NUDT16L1 in open-access papers:
NUDT16L1 is named in the same sentence as 17 diseases in open-access papers, as found by Europe PMC text mining. Sharing a sentence is not in itself a finding about the gene and the disease. The quoted sentences say what the papers report.
glioma (1 paper, 2024). A benign or malignant brain and spinal cord tumor that arises from glial cells (astrocytes, oligodendrocytes, ependymal cells). "Moreover, the variance in expression levels of DCPS, EIF4E1B, NUDT1, and NUDT16L1 between glioblastomas (GBMs) and low-grade gliomas (LGGs) suggests their involvement in the progression of glioma malignancy." (PMID 39061374, 2024).
NUDT16L1 also shares sentences with these, for which no sentence is quoted: cancer (8 papers); tumor (6); prostate carcinoma (2); breast carcinoma (1); breast invasive carcinoma (1); cholangiocarcinoma (1); ciliopathies (1); colon cancer (1); colorectal carcinoma (1); degenerative diseases (1); diffuse large B-cell lymphoma (1); Joubert syndrome (1); metabolic disease (1); neurological disorders (1); primary ciliary dyskinesia (1); retinitis pigmentosa (1).